BCL2A1 (BCL2 related protein A1)
Diseases named in the same sentence as BCL2A1 in open-access papers (continued):
Sharing a sentence is not in itself a finding about the gene and the disease.
cancer (continued). "BCL2-related protein A1 (BCL2A1) is a member of the BCL-2 protein family, and its related pathways include apoptosis, autophagy, and ALK signaling in cancer." (PMID 37056387, 2023). "Staining for either BCL2A1 or AIM2 revealed that both are correlated with pN status, extranodal extension, clinical stage and cancer-specific survival (CSS)." (PMID 33391539, 2021). "One such route frequently utilized by cancer cells is upregulation of the antiapoptotic BCL2 family proteins, including BCL2, MCL1, BCL2A1, and BCLxL." (PMID 30635584, 2019). "In contrast to these three main anti-apoptotic BCL2 proteins, the genes for the related anti-apoptotic BCL2 proteins Bfl1 (BCL2A1), BCL-w (BCL2L2) and BCL-B (BCL2L10) display little perturbation effects in cancer (mean Chronos Gene Dependency Scores −0.0454, −0.103 and 0.006, respectively)." (PMID 40113751, 2025). "BCL2A1, a member of the BCL2 family, is overexpressed in various cancer cells and may contribute to tumour progression." (PMID 40122572, 2025). "BCL2-related protein A1 (BCL2A1), an antiapoptotic protein, promotes anti-cancer drug resistance." (PMID 38214842, 2024). "LGALS1 and BCL2A1 may play roles in promoting cancer in AML, while ELANE may have a significant effect on suppressing cancer." (PMID 38205232, 2024). "While MCL1, BCL2L1, or BCL2L2 were ubiquitously expressed, BCL2 and BCL2A1 demonstrated tissue/lineage-selective expression with very low/no expression across most of the cancer cell lines and TCGA tumor tissues." (PMID 30635584, 2019). "An intestinal immune network for IgA production might provide new markers in enteric DLBCL, such as CCR10, TNFRSF13B, AICDA, and HLA-DOB, as well as genes involved in transcriptional misregulation in cancer (NFKBIZ, FUT8, LMO2, CCND2, BCL2A1, ETV6, and CDK14)." (PMID 29992138, 2018). "B-cell lymphoma 2-related protein A1 (BCL2A1) is a member of the BCL-2 family of anti-apoptotic proteins that confers resistance to treatment with anti-cancer drugs; however, there are presently no agents that target BCL2A1." (PMID 29760958, 2018). "As there is no effective drugs to treat cancers that high expression BCL2A1 at present, the discovery of its target drug could provided value to guide clinical treatment." (PMID 36524001, 2022). "Concomitant expressions of IL-17A, with or without IFN-γ, pro-angiogenic VEGF, pro-survival BCL2A1 and suppressive IL-10 or free radical peroxynitrite may indicate that IL-17A strongly supports cancer development." (PMID 23441221, 2013). "A model has been proposed that SF3B-targeting splicing modulators preferentially perturb RNA splicing of MCL1 and BCL2A1, but not of BCL2L1 (BCLxL), leading to selective cytotoxicity in MCL1- or BCL2A1-dependent cancer cells." (PMID 37562845, 2023).
tumor (64 papers, 2002 to 2025). "In treatment-naive samples, Mono_EREG exhibited high expression of CCL family genes (CCL3L3, CCL20), EREG, and BCL2A1, which are associated with tumor progression, suggesting functional impairment." (PMID 40725006, 2025). "The discovery of BCL2A1+tissue-resident macrophages expands our understanding of tumor-associated macrophage (TAM) heterogeneity." (PMID 40707992, 2025). "We have previously shown that overexpressing BCL2A1 in tumor cells make them less susceptible to MCL1 inhibitor." (PMID 38459020, 2024). "We have previously found that BCL2A1 is associated with decreased sensitivity to MCL1 inhibition in tumor cells." (PMID 38459020, 2024). "The results showed that either BCL2A1 or AIM2 staining was significantly associated with PSCC tumor progression, as indicated by clinical features including the pN status, clinical stage and ENE." (PMID 33391539, 2021). "In contrast, endogenous amplification/high expression of MCL1 or BCL2A1, which confers “oncogene addiction” in tumor cells, is associated with hypersensitivity to E7107-induced cell death." (PMID 30635584, 2019). "Our results demonstrate that BCL2A1+macrophages are present in both tumor tissues and adjacent normal tissues and are associated with poor prognosis in WT patients, suggesting their potential role in tumor progression." (PMID 40707992, 2025). "Interestingly, bioinformatic prediction and immunohistochemical/immunofluorescence staining analysis revealed that BCL2A1 expression was obviously associated with the tumor-associated macrophages (TAMs) markers CD68 and CCL2." (PMID 37889551, 2023). "Therefore, we investigated the association of BCL2A1 with tumor-associated macrophage markers through the TCGA, CGGA, Rembrandt and Gravendeel databases." (PMID 37889551, 2023). "However, differential gene expression and functional enrichment analyses showed that tumor-associated BCL2A1+macrophages are enriched in pathways related to immune response regulation, apoptosis, and NK cell–mediated cytotoxicity, suggesting their involvement in immune modulation within the TME." (PMID 40707992, 2025). "scRNA-seq data showed that BCL2A1+macrophages in tumor and normal tissues had highly similar expression of macrophage marker genes (such as CD68 and CD163), indicating consistent fundamental macrophage characteristics." (PMID 40707992, 2025). "These insights provide a new perspective on the role of BCL2A1+macrophages in tumor progression and lay the groundwork for developing individualized immunotherapeutic strategies targeting macrophages." (PMID 40707992, 2025). "This study is the first to identify the presence of a BCL2A1+tissue-resident macrophage subset in WT and reveal its critical role in tumor progression, potentially providing a novel target for personalized immunotherapy." (PMID 40707992, 2025). "Immunohistochemical staining of paraffin-embedded sections from 48 WT patients revealed that the positive staining rate of BCL2A1 progressively increased with advancing tumor stages." (PMID 40707992, 2025). "In glioblastoma, BCL2A1 promotes tumor progression and affects patient prognosis by participating in TAM infiltration." (PMID 40707992, 2025). "We aim to understand the expression of BCL2A1 in these subpopulations and explore its relationship with tumor progression and the immune microenvironment." (PMID 40707992, 2025). "According to our findings, SPP1+BCL2A1+ TAMs were consistently enriched in tumor tissues compared with adjacent normal liver, and their abundance strongly correlated with poor response to PD-1 blockade." (PMID 41225975, 2025). "In summary, BCL2A1 expression in WT is related to tumor stage and has certain prognostic predictive value in the short term." (PMID 40707992, 2025). "Comparative boxplot analyses confirmed significantly elevated SPP1+BCL2A1+ TAM scores in tumor versus normal tissues (p < 0.05)." (PMID 41225975, 2025).
tumor (continued). "Comparative analysis of BCL2A1+macrophages from tumor and adjacent normal tissues revealed highly similar expression of macrophage marker genes (e.g., CD68, CD163)." (PMID 40707992, 2025). "Overexpression of BCL2A1 enhances tumor cell survival and resistance to pro-apoptotic agents like TNF-α42." (PMID 40739397, 2025). "The positive rate in stage I and II patients was markedly lower than that in stage III and IV patients (p < 0.001), further confirming the correlation between BCL2A1 expression and tumor progression." (PMID 40707992, 2025). "In summary, this study reveals for the first time two critical macrophage subpopulations in WT: the known pro-tumor M2 macrophages and the newly identified BCL2A1+macrophage subpopulation." (PMID 40707992, 2025). "Statistical analysis demonstrated significantly elevated SPP1+BCL2A1+ TAMs scores in tumor tissues (p < 0.0001), establishing this newly identified TAM subtype as an HCC-enriched immune subset." (PMID 41225975, 2025). "Previous studies have demonstrated that these two drugs can inhibit tumor progression, and another study has confirmed that inhibition of BCL2A1 expression increases the sensitivity of blood cancers to imatinib." (PMID 39834939, 2024). "Despite its significance, BCL2A1 has a brief half‐life, largely due to ongoing processing by the ubiquitin–proteasome system, which serves as a crucial tumor‐suppressor mechanism governing BCL2A1 activity." (PMID 39534556, 2024). "The results confirmed that BCL2A1 was positively correlated with this series of tumor-related macrophage markers, especially CCL2 and CD68." (PMID 37889551, 2023). "Inhibiting the expression of BCL2A1 effectively inhibited the proliferation of tumor cells and improved the prognosis of mice in vitro and in vivo." (PMID 37889551, 2023). "As we suspected, mice implanted with BCL2A1 knockdown cells produced smaller tumor volumes than controls, and Kaplan-Meier analysis demonstrated that the BCL2A1 knockdown group mice have a longer survival time than control group mice." (PMID 37889551, 2023). "BCL2A1 represses hypoxia-induced cell death and mitochondria-mediated apoptosis and promotes tumor growth and metastasis." (PMID 35060926, 2022). "The expression levels of EIF4EBP1 and BCL2A1 in BC patients are significantly higher than those in normal breast tissues, and with the increase of tumor malignancy." (PMID 36524001, 2022). "Although tumor heterogeneity is a challenge in the use of genomic-based prognostic markers 40, our results suggest the low intratumor variability of BCL2A1 and AIM2 during tumor progression." (PMID 33391539, 2021). "When subjected to various types of tumor developments and progression stresses, the BCL2A1 mitochondrial localization was increased." (PMID 34572804, 2021). "The average number of tumor nodules formed by the BCL2A1−/− OVCA433 cells was 8% of that formed by the scrambled control cells (p = 0.0002)." (PMID 34572804, 2021). "We found that knockout of BCL2A1 in ES-2 (BCL2A1−/− ES-2) cells significantly reduced tumor nodule formation and improved the survival rate of SCID mice that were i.p. injected with ES-2 scrambled control cells." (PMID 34572804, 2021). "The weight of the tumor nodule formed by BCL2A1−/− OVCA433 cells was 55% less than that formed by the scrambled control cells (p = 0.0281)." (PMID 34572804, 2021). "Apart from that, MCPIP1 is recognized as a tumor suppressor due to its induction of apoptosis of tumor cells, for instance by selectively enhancing mRNA decay of antiapoptotic gene transcripts, including Bcl2L1, Bcl2A1, RelB, Birc3, and Bcl3." (PMID 31651935, 2019). "In our study, MITF and BCL2A1 were expressed in the melanospheres at levels similar to those in the tumor samples, which were higher than in the monolayers." (PMID 24733089, 2014). "All cases analyzed were similarly positive for BCL2A1, suggesting that the overexpression of BCL2A1 is important for promoting survival in both tumor types." (PMID 23741337, 2013).
tumor (continued). "IHC results demonstrated that BCL2A1 was expressed in the renal tubular epithelial cells of adjacent normal tissues, with punctate BCL2A1-positive regions similar to those observed in tumor tissues, indicating that BCL2A1 is also expressed in macrophages of normal tissue." (PMID 40707992, 2025). "However, the high expression of BCL2A1 in specific macrophage subpopulations significantly impacts tumor progression." (PMID 40707992, 2025). "BCL2A1+macrophages may influence tumor progression through apoptosis regulation and modulation of immune responses, whereas CD163+macrophages may be involved in antigen presentation." (PMID 40707992, 2025). "The presence of SPP1+BCL2A1+ TAMs is associated with an immunosuppressive tumor microenvironment in non-responders." (PMID 41225975, 2025). "However, drug resistance mechanisms are simultaneously enhanced in tumor cells, primarily due to increased production of the apoptosis regulators BCL2A1 and cIAP2." (PMID 41465443, 2025). "Notably, BCL2A1+macrophages exhibited significant differences from CD163+macrophages within tumor tissues." (PMID 40707992, 2025). "Inhibiting the expression or function of BCL2A1 may reduce the pro-tumor effects of these macrophages, thereby improving patient outcomes." (PMID 40707992, 2025). "We hypothesize that BCL2A1+macrophages play a crucial role in the progression of WT by modulating the immune microenvironment and facilitating tumor growth." (PMID 40707992, 2025). "Notably, knockdown of BCL2A1 significantly inhibited cell proliferation of U87 and U251 in vitro, induced smaller tumor size and prolonged survival time of mice in vivo." (PMID 37889551, 2023). "BCL2A1 was negatively correlated with tumor purity and positively correlated with immune cells." (PMID 36524001, 2022). "Hence, these findings indicate that BCL2A1 is significantly involved in tumor dissemination in the murine peritoneal cavity." (PMID 34572804, 2021). "Besides this, similar to PD-L1, CCL18 and BCL2A1 were also significantly positively correlated with TME score (stromal, immune, and ESTIMATE scores), whereas negatively associated with tumor purity." (PMID 35265629, 2021). "However, significant differences in BCL2A1 expression were observed across different tumor stages." (PMID 40707992, 2025). "Besides, BCL2A1 is overexpressed in various neoplastic cells, including hematological malignancies and solid tumors, and is known to contribute to tumor progression." (PMID 34833004, 2021). "Therefore, with the advantages of the molecular classifiers BCL2A1 and AIM2, we identified a small proportion of pN0 patients (17.6%, 19/108) at high risk of tumor progression and poor outcomes, a subset that was imperceptible by conventional pT or G stratification." (PMID 33391539, 2021). "We speculate that both BCL2A1 and AIM2 are implicated in the tumor proliferation of PSCC." (PMID 33391539, 2021). "This tumor was the first hematopoietic malignancy reported in a recipient of primitive cells transduced with a replication-incompetent vector containing only marker genes, and suggested that BCL2A1 could have potent effects on hematopoiesis." (PMID 23118966, 2012). "To examine MDSC-tumor interactions, we analyzed the GSE145374 dataset, identifying CSF2, SAA2, IL6, SAA1, and BCL2A1 as the top five upregulated differentially expressed genes in SKOV3 cells after co-culture with MDSCs." (PMID 41029721, 2025). "IHC results demonstrated significant expression of BCL2A1, CD68, and CD163 within the tumors, with BCL2A1 exhibiting a distribution pattern highly similar to that of CD68 and CD163, primarily localized in the tumor stroma region." (PMID 40707992, 2025). "In contrast, CDKN1A upregulation reinforced the cell cycle arrest observed in tumor cells, while FABP1 and BCL2A1 suggest metabolic and apoptotic adjustments in the post-knockdown state." (PMID 41411347, 2025).
tumor (continued). "While SPP1+ TAMs are known to promote tumor progression through immunosuppressive mechanisms, the SPP1+BCL2A1+ TAM subset further exhibits a distinct transcriptional program associated with resistance to cell death." (PMID 41225975, 2025). "In the tumor tissue stage, monocytes remain active in the TME, interacting with tumor cells and other immune cells, marked by elevated expression of CXCL8, NAMPT, AQP9, and BCL2A1." (PMID 38720887, 2024). "Analysis of their expression levels in tumor patients and normal subjects identified five core prognostic markers, which were EIF4EBP1, BCL2A1, NDRG1, ERRFI1 and BRD4." (PMID 36524001, 2022). "Consistent with the CGP results, the mRNA expression of BCL2A1 and AIM2 was higher in 78 tumor tissues than in 21 normal tissues." (PMID 33391539, 2021). "Further analysis of the mRNA expression of 15 pairs of PSCC and N tissues showed that BCL2A1 and AIM2 were overexpressed in tumor tissues compared with the corresponding control tissues, consistent with the WB results." (PMID 33391539, 2021). "The results showed that BCL2A1 and AIM2 proteins were highly expressed in tumor tissues and PSCC cells compared to normal controls." (PMID 33391539, 2021). "We determined that knocking down BCL2A1 and AIM2 inhibited PSCC cell proliferation, clone formation, migration in vitro and tumor growth in vivo, supporting their critical role in tumorigenesis." (PMID 33391539, 2021). "To further study potential pathways for chemotherapy-sensitive tumor cells to benefit from immunotherapy and the molecular mechanisms of CCL18 and BCL2A1, we performed GSEA among 186 KEGG pathways, including the Toll-like receptor signaling pathway." (PMID 35265629, 2021). "The profiling data showed that 7 apoptosis-related genes were concordantly > twofold downregulated in recurrent tumor samples compared with the expression in paired primary tumor samples, including AKT1, BAG4, BCL2A1, BFAR, CARD6, CASP8 and TNFRSF21." (PMID 34488754, 2021). "With the regulation of the tumor microenvironment, more genes were upregulated with over two-fold differences in both HK1 and C17 xenografts after CYLD knockout, including BCL2A1, CXCL1, BIRC3, SERPINB2, total VEGF, TNFA, and VEGFA." (PMID 32708712, 2020). "Although the key-role of MCL-1 or BCL-2 in tumor cell survival and drug resistance is undisputed, little is known about the relevance of related BCL2A1/A1 (called BFL-1 in humans), a poorly investigated member of the BCL-2 family." (PMID 27694901, 2017). "In addition to BCL2A1 expression, we also identified a pre-M2 phenotype in IL-17A-treated DC, opening the view that, in the absence of IFN-γ, IL-17A-dependent myeloid cell plasticity may give rise to M2-like tumor-associated macrophages." (PMID 23441221, 2013). "In the apoptosis signaling pathway, the downregulation of apoptosis-related genes, such as BCL2-related protein A1 (BCL2A1), may inhibit the survival and proliferation of tumor cells, thereby suppressing tumor growth." (PMID 40429988, 2025). "In our analysis, we found that MDSCs coexpressed high levels MCL1 and BCL2A1, but not any of the other populations of tumor-infiltrating myeloid cells captured in our analysis." (PMID 38459020, 2024). "Depletion of the NCOA3-p300-NF-κB components or blockage of NCOA3 function with inhibitors (gossypol and bufalin) in ER-positive cells suppressed BCL2, BCL2A1, BCL2L2, and MCL1 expression, while also decreasing cell viability, colony formation, cell invasion, and tumor growth." (PMID 36853387, 2023). "The tumor nodules on the omentum and mesenterium were examined by H&E staining, IHC, and Western blot analysis to confirm the expression of BCL2A1 in the tumor cells with or without BCL2A1 gene knockout." (PMID 34572804, 2021).
tumor (continued). "The differential expression patterns of BCL2A1+macrophages in tumors and normal tissues further support the"subversion hypothesis,"which posits that the TME can"subvert"tissue-resident macrophages to acquire abilities that promote tumor growth and metastasis." (PMID 40707992, 2025).